ADSL (adenylosuccinate lyase)
Diseases named in the same sentence as ADSL in open-access papers (continued):
Sharing a sentence is not in itself a finding about the gene and the disease.
cancer (10 papers, 2019 to 2025). A tumor composed of atypical neoplastic, often pleomorphic cells that invade other tissues. "Abnormal adenylosuccinate lyase (ADSL) activity is associated with cancer and neurodevelopmental processes." (PMID 41283386, 2025). "As a part of the de novo purine nucleotide biosynthesis pathway, partial loss of ADSL activity is expected to suppress the proliferation of cancer cells." (PMID 41283386, 2025). "Although ADSL is closely related to the progression of various cancers, the exact molecular mechanisms underlying the expression of Dicer and ADSL remain elusive." (PMID 37976135, 2023). "Indeed, according to The Cancer Gene Atlas, the overexpression of ADSL is associated with unfavorable prognosis of liver cancer patients." (PMID 41283386, 2025). "The ADSL gene was discovered to have potential role in breast and prostate malignancies early in 1987, and has been found to be up-regulated in a variety of cancer types." (PMID 40313243, 2025). "ADSL silencing significantly upregulated the mRNA and protein expression levels of cancer stem cell–related transcription factors, namely, Oct-4, Nanog, KLF4, and SOX4, as indicated by qRT-PCR and Western blotting." (PMID 37976135, 2023). "Recent work also implicated ADSL in the activation of MYC, which plays a major role in controlling metabolism and proliferation in cancer cells." (PMID 35133277, 2022). "In comparison, the well-known oncogene PIK3CA was found critical in 29 cell lines, further strengthening the importance of studying ADSL in cancer." (PMID 31729379, 2019). "With further improvement in its permeability, compounds derived from 1 might be useful for the study of ADSL in vivo and for suppressing the growth of ADSL-dependent cancer cells." (PMID 41283386, 2025). "Thus, ADSL activity can promote or suppress proliferation of cancer cells in a context-dependent manner." (PMID 41283386, 2025). "For these types of cancer cells, inhibitors of ADSL might be beneficial." (PMID 41283386, 2025). "In addition, ADSL activity is also connected to cancer in a complex manner." (PMID 41283386, 2025). "However, the role of ADSL in cancer, especially TNBC, remains elusive." (PMID 31729379, 2019). "Our results are in line with the current literature reporting that ADSL indirectly modulates Akt phosphorylation and c-MYC activation in other cancer types 6,7." (PMID 33754045, 2021). "Furthermore, ADSL overexpression reversed Dicer silencing induced DTIC resistance and cancer stemness." (PMID 37976135, 2023). "Moreover, we observed that changes in ADSL levels affected Dicer-mediated DTIC sensitivity and cancer stemness." (PMID 37976135, 2023).
infection (9 papers, 2017 to 2023). The state of being infected such as from the introduction of a foreign agent such as serum, vaccine, antigenic substance or organism. "The purB gene (GAM18), which encodes an adenylosuccinate lyase involved in the biosynthesis of purines, has been described as essential for rhizosphere colonization by Pantoea agglomerans and for infection thread formation and nodule development in Lotus japonicus induced by Mesorhizobium loti." (PMID 30478234, 2019). "The consequences of ADSL deletion on the acute infection stage of the parasite were studied by performing a survival curve analysis." (PMID 31935935, 2020).
metabolic disorder (2 papers, 2023 to 2024). "Adenylosuccinate lyase (ADSL) deficiency is a rare inherited metabolic disorder with a wide phenotypic presentation, classically grouped into three types (neonatal, type I, and type II)." (PMID 37842880, 2024). "Adenylosuccinate lyase deficiency is an ultra-rare metabolic disorder associated with muscle and neural dysfunction, including muscle weakness, psychomotor delay, and repetitive vocalizations and behaviors." (PMID 37773959, 2023). "Adenylosuccinate lyase deficiency is an ultrarare congenital metabolic disorder associated with muscle weakness and neurobehavioral dysfunction." (PMID 37773959, 2023).
neurodevelopmental disorder (2 papers, 2020 to 2022). A behavioral and cognitive disorder with onset during the developmental period that involves impaired or aberrant development of intellectual, motor, or social functions. "Among them, only two genes (ADSL and ATIC) were associated with neurodevelopmental disorders." (PMID 32384607, 2020).
colorectal (1 paper, 2021). "Our in vitro and in vivo results provide evidence of the role of ADSL as an oncogene in colorectal carcinogenesis." (PMID 33754045, 2021).
myopathy (1 paper, 2024). A disease of the muscle in which the muscle fibers do not function properly. "Transcriptome analysis of skeletal muscle biopsies from ADSS1 myopathy patients revealed significant downregulation of all three purine nucleotide cycle (PNC) genes: ADSS1, adenylosuccinate lyase (ADSL) and adenosine monophosphate deaminase 1 (AMPD1)." (PMID 39593137, 2024).
ADSL also shares sentences with these, for which no sentence is quoted: autism spectrum disorder (2 papers); bacterial infection (2); AADC deficiency (1); atopic dermatitis (1); cardiac diseases (1); Cirrhosis (1); cystinuria (1); deafness (1); developmental delay (1); dihydropyrimidine dehydrogenase deficiency (1); galactosemia (1); genetic disorders (1); gram-positive bacterial infections (1); hearing loss (1); Hydrocephalus (1); Hypoglycemia (1); Immunodeficiency (1); learning disability (1); Leber congenital amaurosis (1); Lesch-Nyhan syndrome (1); liver cancer (1); maple syrup urine disease (1); myiasis (1); Neurodevelopmental delay (1); pyrimidine metabolic disorders (1); Rubinstein-Taybi syndrome (1); Seizure (1); skin infection (1); tuberous sclerosis (1); tubular adenoma (1).